CDCA5 (cell division cycle associated 5)
Diseases named in the same sentence as CDCA5 in open-access papers (continued):
Sharing a sentence is not in itself a finding about the gene and the disease.
tumor (continued). "Meanwhile, another tumor suppressor miRNA, hsa-mir-200b, was down-regulated in CDCA5-high patients." (PMID 32694239, 2020). "Furthermore, to explore the mechanism of CDCA5 on BC in vivo, we performed IHC analysis on the tumor mass." (PMID 32201512, 2020). "All these findings indicated that CDCA5 acts as a tumor promoter in BC." (PMID 32201512, 2020). "Recent studies have reported that CDCA5 is overexpressed in some tumor tissues, suggesting that it may act as a promoter in tumor progression 15-20." (PMID 32201512, 2020). "Consistently, it is reported that the knockdown of CDCA5 shows strong inhibition in tumor proliferation, which could be an attractive target for immunotherapy." (PMID 33665158, 2020). "This partially explains the stunted growth of tumor cells after CDCA5 knockdown." (PMID 32201512, 2020). "Using a nude mouse xenograft model bearing HCT116 or HT-29 cells transduced with sh-CDCA5 lentivirus, we found that CDCA5 knockdown could markedly decrease tumor growth." (PMID 30808873, 2019). "Furthermore, CDCA5 expression was higher in tumor tissue than normal hepatic or peritumoral tissue by immunohistochemistry in all 178 samples." (PMID 30497429, 2018). "Furthermore, the expression of CDCA5 in excised tumor tissue was markedly suppressed, by 53%, in the group treated with siCDCA5." (PMID 26497678, 2016). "In addition, CDCA5 was found to be significantly upregulated in human tumor tissues, including HCC." (PMID 38890649, 2024). "Meanwhile, DNA methylation might be responsible for the aberrant level of CDCA5 in tumor tissue." (PMID 37287817, 2023). "Therefore, high expression of CDCA5 could play a significant role in tumor progression, invasion, and metastasis via cyclin E1." (PMID 36428736, 2022). "During BC angiogenesis, BC stem cell transcription factors and mammosphare formation (such as; tumor size and number of tumor spheroids) were reported to be significantly elevated as a results from the induced of CDCA5 expression, which might highlight its role in tumor progression and development." (PMID 36428736, 2022). "CDCA5 is also positively associated with other well-established cell cycle factors such as cell division cycle protein 2 (CDC2) and cyclin B1 and it plays a key role in the phosphoinositide 3-kinase (PI3K)/AKT/mTOR signaling pathway, which contributes to tumor progression." (PMID 36428736, 2022). "Across CDCA2, CDCA3, CDCA4, CDCA5, CDCA7, and CDCA8, we observed significantly lower promoter methylation levels in primary tumor samples compared to normal samples, suggesting hypomethylation of these genes in GBM tumors." (PMID 40114265, 2025). "In line with above results, the WB analysis in tumor tissues of mice suggested that the protein levels of FOXM1 and E2F1 were significantly upregulated in CDCA5-overexpressiong tumor tissues." (PMID 38978058, 2024). "Our findings revealed that the expression levels of the hub genes—UBE2T, KIF4A, CDCA3, and CDCA5—were correlated with various clinical aspects of HCC, including cancer stages, nodal metastasis status, tumor grade, and histological subtypes." (PMID 38890649, 2024). "By analyzing the MOD values of 80 pairs of tumor and para-tumor tissue, we found that both CDCA4 and CDCA5 are overexpressed in tumors compared with that in normal tissues (P < .001)." (PMID 38875380, 2024). "By stabilizing CDCA5 protein, TPI1 activates PI3K/AKT/mTOR pathway, thereby enhancing tumor progression and glycolysis." (PMID 35509067, 2022). "The results revealed that CDCA5 and CDCA8 were differentially expressed in tumour and normal tissues of multiple cancer species, showing a tendency of up‐regulation." (PMID 33449451, 2021). "Two hub genes, CDCA5 and ESPL1, identified as probably playing tumor-promotive roles, have great potential to be utilized as novel therapeutic targets for EOC treatment." (PMID 34143800, 2021).
tumor (continued). "After verification of the two selected genes through external databases, we found that: the OS of patients with high expression of CDCA5 and CDCA8 in tumour tissues were significantly decreased from the chip data of GSE4412." (PMID 33449451, 2021). "CDCA5 participated the promotion of HCC cells proliferation, migration, and invasion, palying a tumor-promotive role and being a potential therapeutic target for patients with HCC." (PMID 34143800, 2021). "This study reported that CDCA3, CDCA5, and CDCA8 mRNA expression levels were significantly higher than the control sample in both clinical tumor sample and cancer cell lines, which dramatically reduced patient survival." (PMID 33285689, 2020). "After comparing the expression level of the tumor tissue and the paracancer tissue in each case, we found that the expression levels of CDCA2, CDCA3, CDCA5 and CDCA8 were overexpressed in tumor tissues in each patient." (PMID 32913466, 2020). "In conclusion, our study provided the evidence of CDCA5 as an oncogenic promoter in HCC and its potential function in affecting tumor microenvironment." (PMID 32694239, 2020). "We performed meta-analysis on 8 microarray studies and identified six significantly up- (PLAU, FN1, CDCA5) and down-regulated (CRNN, CLEC3B and DUOX1) genes which were subsequently quantified by RT-qPCR in 100 HNSCC patient margin and core tumour samples." (PMID 31443700, 2019). "IHC showed that CDCA5 knockdown (P < 0.05 vs. sh-Ctrl) significantly decreased proliferating cell nuclear antigen (PCNA) expression in xenograft tumor (P < 0.05 vs. sh-Ctrl)." (PMID 30808873, 2019). "CDCA5 was found to be upregulated in 4 OSCC cell lines and its knockdown led to tumour cell growth inhibition in vitro and in vivo." (PMID 31443700, 2019). "In summary, CDCA5, FOXM1, KIF15, MCM2, and ZWINT was involved in cell mitosis and supported our research results by affecting the cell cycle regulation of tumor pathogenesis." (PMID 31708970, 2019). "The present study found that CDCA5 overexpression in HCC was correlated with decreased survival, increased microvascular invasion, and increased tumor size in a real patient population." (PMID 30497429, 2018). "CDCA3, CDCA5, and CDCA8 mRNA expression levels were significantly higher than the control sample in both clinical tumor sample and cancer cell lines." (PMID 29467944, 2018). "To confirm the usefulness of targeting CDCA5 in OSCC, we established primary cell cultures from newly resected tumor tissues from patients with OSCC." (PMID 26497678, 2016). "In addition, based on IHC, expression levels of CDCA5, Ki67, p-mTOR, and LDHA were higher in tumor tissue generated by TPI1 overexpression cells than vector control; E-cadherin was lower in these tumors." (PMID 35509067, 2022). "A further study conducted in our laboratory on a gamma-irradiated resistant oral keratinocyte cell line demonstrated that the downregulation of PLAU, FN1 and CDCA5 appeared to be indicators of the tumour being resistant to radiation therapy (data not shown)." (PMID 31443700, 2019). "Notably, CDCA3, CDCA4, CDCA5, and CDCA8 exhibited elevated expression trends in the radiation-resistant cohorts, consistent with the TCGA-READ database findings showing preferential CDCA family overexpression in tumor specimens." (PMID 40565588, 2025). "Most of the CDCA5 expression in OSCC tissues was observed in tumor cells but not stromal cells." (PMID 26497678, 2016). "We investigated the expression of ASPM, CCNB2, CDCA5, KIAA0101, PRC1, and UBE2T in 12 LUAD tumor tissues and their adjacent non-malignant lung tissues." (PMID 33937050, 2021).
cancer (46 papers, 2007 to 2026). A tumor composed of atypical neoplastic, often pleomorphic cells that invade other tissues. "We subsequently explored the correlation between genetic mutations in CDCA5 and clinical outcomes of cancer patients." (PMID 38213717, 2024). "Cell division cycle associated 5 (CDCA5), a master regulator of sister chromatid cohesion, was reported to be upregulated in several types of cancer." (PMID 38978058, 2024). "Due to recent advancements in bioinformatics, it is now known that CDCA5 is linked to poor prognosis of various carcinomas." (PMID 38539247, 2024). "The gene cell division cycle associated 5 (CDCA5), also called sororin, has oncogenic characteristics and is upregulated in various carcinomas." (PMID 38539247, 2024). "Several studies have been conducted to investigate the role of cell division cycle-associated 5 (CDCA5) in cancer." (PMID 37287817, 2023). "Literature retrieval showed that the expression of CDCA5 was associated with tumorigenesis and tissue invasion in a variety of cancers, while the results on the roles of ESPL1, CDC45, and ESPL1 in cancers were conflicting." (PMID 34143800, 2021). "The upregulation of cell division cycle associated protein 5 (CDCA5) has been observed in various cancer types." (PMID 32694239, 2020). "Overall (with exceptions), the 3 upregulated genes (PLAU1, FN1 and CDCA5) were generally associated with poor prognosis in these cancer types when gene expression levels were upregulated." (PMID 31443700, 2019). "Cell division cycle associated 5 (CDCA5) is implicated in the development and progression of a variety of human cancers." (PMID 30808873, 2019). "We have attempted to find appropriate molecular targets for OSCC and identified cell division cycle associated 5 (CDCA5) as a cancer-related gene which was overexpressed in all the human OSCC cells tested by microarray analysis." (PMID 26497678, 2016). "Thus, we have shed light on the association between CDCA5 expression level and immune cell infiltration in certain cancers." (PMID 38213717, 2024). "Cancers with elevated CDCA5 expression levels are associated with a dismal prognosis for overall survival (OS), such as ACC (P=2.5E-06), KIRC (P=0.0097), KIRP (P=0.0082), LGG (P=0.00026), LIHC (P=0.00021), LUAD (P=0.0056), MESO (P=9.7e-08), PAAD (P=0.024), PRAD (P=0.025), and SKCM (P=0.016)." (PMID 38213717, 2024). "Collectively, our research illuminates the underlying role of CDCA5 in cancer immunity." (PMID 38213717, 2024). "Cell division cycle associated 5 (CDCA5) plays ontogenetic role in various human cancers." (PMID 38658931, 2024). "In addition, CDCA5 affects the activity of transcription factors and proteins associated with the cell cycle; it thus promotes cancer cell growth and participation in apoptosis." (PMID 38213717, 2024). "Notably, IGF2BP1 (insulin-like growth factor 2 mRNA binding protein 1), MIR192 (microRNA mir-192), and CACD5 (cell division cycle associated 5) are significantly enriched in the KEGG pathway of MicroRNAs in cancer." (PMID 39273692, 2024). "Cell division cycle-associated 5 (CDCA5) has been widely studied in human cancer progression." (PMID 36741311, 2023). "Cell division cycle associated 5 (CDCA5), originally recognized as a substrate that promotes late complexes, has been reported to be associated with the development and progression of multiple human cancers." (PMID 37457582, 2023). "Additionally, CDCA5 may influence the activity of cell cycle-associated proteins and transcription factors, influencing cancer cell proliferation and death." (PMID 37287817, 2023). "We evaluate all of these factors to investigate the potential molecular mechanism of CDCA5 in the progression or clinical prognosis for various cancers." (PMID 38213717, 2024). "A growing body of evidence suggests that CDCA5 is involved in the progression of several types of cancers." (PMID 38658931, 2024).
cancer (continued). "In our study, we discovered that CDCA5 is highly expressed in the majority of cancers and is extensively expressed in a range of organs." (PMID 38213717, 2024). "Studies in different cancer types have identified specific signaling pathways and regulators involved in CDCA5-mediated functions." (PMID 38658931, 2024). "Emerging papers have suggested a functional connection between CDCA5 and clinical pathologies, including cancer 7-10." (PMID 38213717, 2024). "The presence of CDCA5 has been found to exhibit a notable correlation with the infiltration of immune cells across a multitude of cancers within The Cancer Genome Atlas Program (TCGA) database." (PMID 38539247, 2024). "Increased CDCA5 expression has been observed in various cancer types, including bladder cancer, lung cancer, liver cancer, colorectal cancer, indicating its potential involvement in the development of these diseases." (PMID 38658931, 2024). "Our findings demonstrated that CDCA5 promoted cancer cell growth and inhibited apoptosis in vitro, which were consistent to the bioinformatic analyses." (PMID 38213717, 2024). "We conducted the first pan-cancer analysis of CDCA5 using data from the TCGA project and the GEO database." (PMID 38213717, 2024). "In most of the designated cancer types, the matching heatmap data likewise revealed a positive connection between CDCA5 and the mentioned five genes." (PMID 38213717, 2024). "We examined the correlation between CDCA5 expression and immune cell infiltration levels in various types of cancer using TCGA data." (PMID 38213717, 2024). "Integrating information on the CDCA-binding proteins and the genes related with CDCA5 expression across the various cancer types, the findings of enrichment analysis showed the potential function of CDCA5 protein." (PMID 38213717, 2024). "In order to investigate the significance of the CDCA5 genein OC, initially, the expression levels of CDCA5 in malignant tumors were examined using the Gene Expression Profiling Interactive Analysis (GEPIA) website." (PMID 38539247, 2024). "It is noteworthy that a strong correlation (P<0.05) between CDCA5 and checkpoint gene expression was observed, which was found to be associated with immune gene CD276 in various types of cancer." (PMID 38213717, 2024). "Using the UALCAN dataset, an analysis of the methylation levels of the CDCA5 gene promoter showed the possible role of CDCA5 across all cancer types." (PMID 38213717, 2024). "We categorized cancer cases into high and low expression groups based on the level of CDCA5 expression, and primarily utilized TCGA and GEO datasets to assess the correlation between CDCA5 expression and patient prognosis across various cancers." (PMID 38213717, 2024). "The expression status of CDCA5 was analyzed across multiple TCGA cancer types utilizing the TIMER2 method." (PMID 38213717, 2024). "An in vitro study in gastric cancer showed that CDCA5 knockdown reduces cancer cell migration and promotes cancer cell apoptosis by inducing G2/M arrest." (PMID 36428736, 2022). "CDCA5 appears to play a significant role in cancer cell proliferation, migration, invasion and metastasis." (PMID 36428736, 2022). "The role of CDCA5 in cancer has been gradually revealed, while the role of CDCA5 as an oncogene in more tumors remains to be discovered." (PMID 35726220, 2022). "shRNA interference technology can knock down the expression of CDCA5 and inhibit its “promoting cancer” effect." (PMID 35726220, 2022). "Remarkably, CDCA5 had been found to have oncogenic activity by disrupting the balance of proliferation and apoptosis in cancer cells." (PMID 36233194, 2022). "Some studies showed that the role of CDCA5 in the regulation of cancer cells is mainly reflected in promoting cancer development." (PMID 35726220, 2022). "Recent studies have correlated the expression of CDCA5 with tumorigenesis and tissue invasion in several cancers." (PMID 34143800, 2021).
cancer (continued). "Among these genes, CDCA5, FOXM1, KIF15, MCM2, and ZWINT were the most reported genes associated with cancer progression, including EOC." (PMID 31708970, 2019). "The CCLE analysis of CDCA5 in cancer cell lines revealed a high expression of this gene, at greater than nine-fold compared to normal control sample." (PMID 29467944, 2018). "Although CDCA5 is increasingly recognized as an oncogene in various malignancies, the exact mechanisms by which CDCA5 promotes cancer progression remain unclear." (PMID 38658931, 2024). "The question of whether CDCA5 can have a role in the pathogenesis of a variety of cancers via shared molecular processes is unsolved." (PMID 38213717, 2024). "In addition, increased CDCA5 expression is highly related to the advanced stage of cancer, indicating malignant development." (PMID 38213717, 2024). "Analysis of disease-free survival (DFS) data demonstrated that cancers with high CDCA5 expression have a poor prognosis of ACC (P=6.6e-05), KIRC (P=0.043), KIRP (P=0.00028), LGG (P=0.0064), LIHC (P=0.00014), MESO (P=0.019), PAAD (P=0.025), PCPG (P=0.03), PRAD (P=0.00048), and THCA (P=0.012)." (PMID 38213717, 2024). "The association between CDCA5 and immunological checkpoints in LIHC, KIRC, BLCA, COAD and THCA was positive, so it is not difficult to comprehend why CDCA5 overexpression was related with a bad prognosis in these four cancers." (PMID 38213717, 2024). "TOP2A, CENPF, TROAP, CDC20, CDCA5, and UBE2C are all reported to be associated with cancer." (PMID 36932399, 2023). "In general, CDCA5 is identified as an oncogene and has a poor prognosis for cancers." (PMID 36741311, 2023). "Furthermore, the functional assessment of CDCA5 in BC is warranted to evaluate its role in cancer cell adhesion pathways." (PMID 36428736, 2022). "Furthermore, as evinced in our study, silencing of CDCA5 expression revealed a significant reduction in migratory and invasive capabilities in BC cell lines, showing the potential of CDCA5 to regulate cancer cell migration among aggressive cancer types." (PMID 36428736, 2022). "The results showed that the protein expression of CDCA5 in MDA-ME-231 and BT549 cells in the control group was significantly higher than that in the negative control group (P < 0.05); that is, the expression of CDCA5 in TNBC cancer cells was higher than that in normal breast cells." (PMID 35726220, 2022). "This may be explained by pro-oncogenic role of CDCA5 during the cell cycle that impairs cancer apoptosis while promoting cell proliferation via the PI3K/AKT/mTOR signalling pathway, which was shown on our results at transcriptomic level." (PMID 36428736, 2022). "Cell division cycle associated 5 (CDCA5), a substrate of the anaphase-promoting complex, was reported to be upregulated in several types of cancer; however, the function of CDCA5 in BC remains unclear." (PMID 32201512, 2020). "Consistent with CDCA5 overexpression in cancer cells, knockdown of CDCA5 could inhibit cancer growth by arresting the cell cycle in the G2/M phase and promoting apoptosis." (PMID 30808873, 2019). "The copy number of CDCA5 was also high in breast and other cancers." (PMID 29467944, 2018). "CDCA5 is a cell cycle regulatory protein that has shown prognostic value in several cancers." (PMID 30497429, 2018). "These genes are involved in the regulation of cell cycle (CCND1, CDCA5, FOSL1, KDM2A, NUMA1, RHOD), apoptosis (FADD, ORAOV1), or the DNA damage response (DDB1, KAT/TIP60, MUS81, PACS1, RPS3), and several have been implicated in the HPV lifecycle and/or HPV-associated cancers." (PMID 40892869, 2025). "However, the role of CDCA5 in more cancer cells requires further exploration." (PMID 35726220, 2022). "In addition, knockdown of CDCA5 could inhibit cancer cell growth by arresting the cell cycle in the G2/M phase and promoting apoptosis." (PMID 33937050, 2021). "Furthermore, CDCA5 regulate cancer cell apoptosis through the mitochondrial apoptosis pathway." (PMID 32201512, 2020).